CDH13 (cadherin 13)
Diseases named in the same sentence as CDH13 in open-access papers (continued):
Sharing a sentence is not in itself a finding about the gene and the disease.
lung carcinoma (28 papers, 2004 to 2026). "In terms of lung cancer, the aberrant methylation status of the APC and CDH13 promoters was associated with lung cancer risk." (PMID 35677637, 2022). "The downregulation of CDH13 was linked to a poorer prognosis in patients with various cancer types, including lung cancer." (PMID 28404957, 2017). "CDH13 or heart cadherin, encoding and adhesion molecule, was identified as DNA hypermethylated in lung cancer in 1998, a finding that was substantiated by many studies." (PMID 21731750, 2011). "CDH13 is a newly identified cell adhesion molecule that is located on chromosome 16q24, a region often exhibiting loss of heterozygosity in cancer, including breast, prostate, colon and lung cancer 26-30." (PMID 32127937, 2020). "Seven tumor suppressor genes (CDKN2A, CDH13, MGMT, MIR137, DAPK1, RARB, and RASSF1A) consistently exhibited hypermethylation in both lung cancer and in association with smoking exposure." (PMID 42073597, 2026). "There is evidence of hypermethylation of the CDH13 promoter in 34% of CDH13 gene aberrant methylation involved in lung cancer pathogenesis." (PMID 37901797, 2023). "Based on lung cancer patient samples, hypermethylation of CDH13 was detected in 57% of cancerous tissues although it was also detected in 2% of the surrounding histologically noncancerous lung tissue." (PMID 37901797, 2023). "In the late nineties, CDH13 hypermethylation at the promoter 5′ region was found in 45% of primary lung cancers, which is responsible for CDH13 gene inactivation." (PMID 37901797, 2023). "It has been more than 20 years since CDH1 and CDH13 methylation were identified in lung cancer, so more insight has been gained into the involvement of both genes’ methylation in lung cancer." (PMID 37901797, 2023). "Abnormal methylation of CDH13 promoter was observed in breast, colorectal, cervical and lung cancers, and chronic myeloid leukemia." (PMID 36315446, 2022). "Our recent study involving a murine model of inflammation-induced lung cancer analogously revealed early epigenetic changes within tumor suppressor genes Rassf1, Cdh13, and Dapk1." (PMID 33396408, 2020). "The hypermethylation in promoter region of CDH13 was frequently observed in lung cancer, and proposed to correlate to drug sensitivity and poorer prognosis." (PMID 31333911, 2019). "One tumor suppressor that is shown to be downregulated and hypermethylated in many cancers (including lung cancer) is cadherin 13 (CDH13)." (PMID 29047229, 2018). "Although hypermethylation of CDH13 is common in breast and lung cancer, there are only a few reports in the literature investigating CDH13 methylation in ovarian cancer." (PMID 23226780, 2012). "The present study examined the relationship between methylation of five genes (p16INK4a, RASSF1A, APC, RARβ and CDH13) and patient survival in 351 cases of surgically resected lung cancers." (PMID 15266335, 2004). "We studied the methylation status of five genes, p16INK4a, RASSF1A, APC, RARβ and CDH13, that are frequently methylated in lung cancers and that are considered to play an important role in the molecular pathogenesis of lung cancers." (PMID 15266335, 2004). "Pol β can demethylate the DNA of the CDH13 promoter, thereby promoting the expression of CDH13 and facilitating cell adhesion and migration functions, which are involved in the regulatory processes of breast and lung cancer." (PMID 39519329, 2024). "In human lung cancer cell lines, the deletion rate of CDH13 is approximately 57%." (PMID 39179585, 2024). "Tumor suppressor gene CDH13, located on chromosome 16q24.2–3, is downregulated in lung cancer and its aberrant methylation may be a potential marker for cancer detection." (PMID 27610375, 2016). "Forced miR-142-3p expression drives proliferation, migration, and chemoresistance in lung cancer and hepatoma lines, whereas miR-142-3p knockdown or pharmacological DNMT1 inhibition restores CDH13 expression and sensitivity to apoptosis induction." (PMID 40649905, 2025).
lung carcinoma (continued). "The methylation levels of eight genes (CALCA, HOXA9, RASSF1A, CDKN2A, DLEC1, CDH13, PITX2, and WT1) in ctDNA were significantly higher in lung cancer patients than in non-lung cancer patients." (PMID 31752198, 2019). "Such previous studies identified the RASSF1A, PITX2, SHOX2, TFPI-2, FHIT, p16, CDH13, and APC genes as predictors of recurrence of lung cancers." (PMID 23544068, 2013). "Two other top genes in African-Americans (CDH13 [MIM 601364] and PTPRD [MIM 601598]) are related to lung cancer and childhood asthma." (PMID 23829686, 2013). "In a silica-induced lung cancer animal model, CDH13 DNA methylation was seen in invasive but not preinvasive lung cancer, and in an analysis of stage I lung cancer patients, it was observed to be associated with recurrent cancer." (PMID 21731750, 2011).
atherosclerosis (22 papers, 2016 to 2025). A disease characterized by the build-up of fatty material and calcium deposition in the arterial wall resulting in partial or complete occlusion of the arterial lumen. "That is why we checked not only the influence of the LDL to HMW adiponectin ratio on the IMT but also the role of single nucleotide polymorphisms (SNPs) in the CDH13 gene (encoding T-cadherin) in early atherosclerosis formation." (PMID 34680515, 2021). "Elevated plasma CDH-13 levels have been associated with early atherosclerosis development, but reduced plasma CDH-13 levels have been associated with a greater severity of coronary artery disease and a higher risk of acute coronary syndrome." (PMID 32396872, 2020). "It is known that the CDH13 encoded protein protects vascular endothelial cells from apoptosis due to oxidative stress and is associated with resistance to atherosclerosis." (PMID 31170924, 2019). "The loss of CDH13 promotes the development of atherosclerosis inhumans and mice." (PMID 40894025, 2025). "In addition, CDH-13 influences vascular function, and has been associated with vascular disorders such as atherosclerosis and hypertension." (PMID 32396872, 2020). "Interestingly, cadherin-13 has been implicated in vascular disease and atherosclerosis and others have found that cadherin-13 overexpression can promote insulin sensitivity while simultaneously reducing the ability to stimulate the Akt pathway." (PMID 32596266, 2020). "Increased CDH13 activity results in increased migration and proliferation of endothelial cells and therefore effects vascular remodeling and atherosclerosis development." (PMID 40182431, 2025). "Cdh13protein levels gradually declined during the development of atherosclerosis inApoe−/− mice on a Westerndiet.Cdh13−/−/Apoe−/−mice on a Western diet developed larger atherosclerotic lesions compared toApoe−/− mice." (PMID 40894025, 2025). "Thus, results from both humansand mice indicate that lower CDH13 expression aggravates atherosclerosis or– vice versa – CDH13 isatheroprotective." (PMID 40894025, 2025). "Thus, we observed reduced arterialexpression of CDH13 during the development of atherosclerosis in bothhumans and mice, suggesting a protective role of CDH13." (PMID 40894025, 2025). "CDH13 has also been shown to be elevated in early atherosclerosis, and ICAM‐1 has been found to be crucial for the development of atherosclerosis." (PMID 35439361, 2022).
cervical cancer (17 papers, 2006 to 2026). A primary or metastatic malignant neoplasm involving the cervix. "The loss or low expression of CDH13 has been observed in a diverse range of cancer types, including cervical cancer, squamous cell carcinoma and melanoma 31-33." (PMID 32127937, 2020). "Besides, Methylated CDH13 could serve as a potential diagnostic and prognostic biomarker in nasopharyngeal carcinoma and cervical cancer, respectively." (PMID 26862903, 2016). "In univariate and multivariate analyses, patients with cervical cancer with unmethylated CDH1/CDH13 in serum had significantly better DFS." (PMID 38110977, 2023). "Promoter methylation of the E-cadherin gene (CDH1) was tested in combination with cadherin 13 (CDH13) in serum samples of 93 cervical cancer patients." (PMID 35725812, 2022). "Hypermethylation was however less frequent in cervical cancer in most genes, particularly in CDH13 (P < 0.001) and TIMP3 (P = 0.025)." (PMID 25065733, 2014). "DNA-methylation status of CDH1 and CDH13 was analyzed by means of MethyLight-technology in serum samples from 49 cervical cancer patients and 40 patients with diseases other than cancer." (PMID 22942707, 2012). "In the present study, we investigated the DNA-methylation status of CDH1 and CDH13 in serum samples from 49 cervical cancer patients and 40 patients with benign diseases." (PMID 22942707, 2012). "Interestingly, the upregulation of the opposing T-cadherin (CDH13) through garcinol was detected in cervical cancer." (PMID 38791932, 2024). "As it is reported CDH1 and CDH13 methylation in serum can be considered as cervical cancer markers." (PMID 31191840, 2019). "Among the 49 PRC2 targets (defined by consistent hyper-MVPs) identified here were 10 genes of the cadherin superfamily in HPV+ HNSCC, including CDH8 and CDH13 (both also hypermethylated in cervical cancer, CDH18, CDH19, CDH23, PCDH10, PCDH15, PCDHB1, PCDHB4, and PCDHB15." (PMID 23419152, 2013). "Methylation of CHFR, CDH13 and CADM1 was only observed in cervical carcinomas and cervical carcinoma cell lines and can as such be designated as relative late events." (PMID 17971771, 2007). "Four loci including DAPK, MGMT, p16 and PTEN were selected for methylation analysis in 127 cervical cancers; APC, CDH13, p16 and hMLH1 were examined in 60 endometrial cancers; and BRCA1, p14, p16 and PTEN in 49 ovarian cancers." (PMID 16928264, 2006). "Specific methylation was found in cervical cancer (including CDH1, DAPK, MGMT and MINT2), endometrial cancer (CASP8, CDH13, hMLH1 and p73), and ovarian cancer (BRCA1, p14, p15, RIZ1 and TMS1)." (PMID 16928264, 2006). "This study was designed to investigate the DNA-methylation status of E-cadherin (CDH1) and H-cadherin (CDH13) in serum samples of cervical cancer patients and control patients with no malignant diseases and to evaluate the clinical utility of these markers." (PMID 22942707, 2012). "Recently, we identified CDH1 and CDH13 DNA-methylation in serum samples taken at the time of diagnosis as an independent prognostic marker in cervical cancer patients with no concurrent chemo- or radiation therapy." (PMID 22942707, 2012). "From the findings of this study, we conclude that serological detection of CDH1 or CDH13 promoter hypermethylation is not able to predict invasive cervical cancers." (PMID 22942707, 2012). "Notably, all eight genes that were frequently methylated in the HPV-transfected cell lines and cervical cancer cell lines (i.e. TP73, ESR1, RARβ, DAPK1, MGMT, CADM1, CDH13 and CHFR) overlapped with those found to be methylated in the cervical carcinoma specimens." (PMID 17971771, 2007).
melanoma (16 papers, 2013 to 2025). A malignant, usually aggressive tumor composed of atypical, neoplastic melanocytes. "Microsatellite analysis led to detection of loss of heterozygosity at the CDH13 locus in thyroid carcinoma, while in the melanoma tissue the c.495G>A variant was in heterozygous state." (PMID 34386506, 2021). "Specifically, in melanoma cells, the transcriptional repression of CDH13 promoter activity by BRN2 enhances their migratory and invasive capabilities." (PMID 40230838, 2025). "Direct regulation of CDH13 expression by transcription factors was reported previously for melanoma cells." (PMID 40649905, 2025). "In this study, we investigated the complex role of T-cadherin (CDH13) with a focus on regulating the sensitivity to garcinol in human melanoma cells." (PMID 38791932, 2024). "If melanoma cell lines express little CDH13, garcinol treatment can lead to an increase in the expression of CDH2, indicating a pro-tumorigenic phenotype of the cells." (PMID 38791932, 2024). "Cluster c5 highly expressed Dkk2, a putative Wnt signaling inhibitor down-regulated in melanoma and Cdh13 (T-cadherin), an adhesion molecule that influences the migration and invasion of melanoma cells and that functions as a pro-apoptotic tumor suppressor." (PMID 39457009, 2024). "Further research is needed to uncover the precise mechanisms and signaling pathways involved in garcinol and CDH13 pharmacodynamics and the implication for CDH13 screening in melanoma patients." (PMID 38791932, 2024). "In melanoma cell lines expressing a small amount of CDH13, garcinol treatment can lead to an increase in the expression of CDH-2, indicating a pro-tumorigenic phenotype of the cells." (PMID 38791932, 2024). "If melanoma cells do express CDH13, they are less sensitive to garcinol in proliferation and FACS analyses." (PMID 38791932, 2024). "Cdh13 was recently shown to function as a pro-apoptotic tumour suppressor that antagonises AKT/CREB/AP-1/FOX03a signalling in melanoma cells." (PMID 28386779, 2017). "The QTL for Deltaproteobacteria (DNA level) on chromosome 8 contains Cdh13, which is expressed in keratinocytes and involved in susceptibility to SCC and malignant melanoma." (PMID 28587635, 2017). "CDH13 gene methylation is also prevalent in melanoma and has been investigated more extensively." (PMID 40230838, 2025). "Furthermore, we showed that melanoma cells expressing T-cadherin (CDH13) respond more sensitively to garcinol treatment." (PMID 38791932, 2024). "Another upregulated gene was CDH13 (Cadherin H), known to participate as a modulator of proliferation and migration in melanoma, SCC and BCC as well as CXCL proteins, involved in the control of epithelial-mesenchymal interaction in normal or malignant epithelial cells." (PMID 28982115, 2017). "In addition, CDH13 expression in melanoma sensitizes to garcinol treatment." (PMID 38791932, 2024). "In addition, CDH13 expression in melanoma cells sensitizes to garcinol treatment." (PMID 38791932, 2024). "Since there was literature suggesting a distinct role of T-cadherin (CDH13) during garcinol treatment, we analyzed the T-cadherin protein status in additional melanoma cell lines next to the melanoma cell lines used here in previous functional assays." (PMID 38791932, 2024). "Ectopic BRN2 expression in BRN2-deficient/T-cadherin-positive melanoma cells led to suppression of CDH13 promoter activity, whereas BRN2 knockdown in BRN2-positive/T-cadherin-negative cells resulted in re-expression of CDH13 mRNA and protein." (PMID 40649905, 2025). "Additionally, certain transcriptional repressors, such as BRN2 in melanoma cells and ZEB1 in gallbladder cancer cells, inhibit the transcriptional activity of the CDH13 promoter." (PMID 40230838, 2025). "However, CDH-2 expression is induced after garcinol treatment and simultaneous CDH13 knockdown, hinting towards an ongoing cancerous cellular phenotype, as CDH-2 is a marker for melanoma progression." (PMID 38791932, 2024).
melanoma (continued). "If melanoma cells do not express CDH13, they are less sensitive to garcinol in proliferation and FACS analyses." (PMID 38791932, 2024). "No other genes explaining the multiple melanoma phenotype have been detected in the patient, whereas WES led to identify only a rare CDH13 truncating variant." (PMID 34386506, 2021).
non-small cell lung carcinoma (14 papers, 2013 to 2025). A group of at least three distinct histological types of lung cancer, including non-small cell squamous cell carcinoma, adenocarcinoma, and large cell carcinoma. "Genetic variants of APOB and CDH13 in the cholesterol pathway have been shown to affect survival in non-small cell lung cancer by modulating gene expression." (PMID 40696350, 2025). "One of these intervals overlapped an intron of the H-cadherin-encoding gene CDH13, for which aberrant promoter methylation and consequent loss of gene expression have been associated with non-small cell lung carcinoma." (PMID 30961659, 2019). "For example, the CDH13 promoter methylation was shown to increase the viability of non-small cell lung cancer cells exposed to cisplatin, by blocking DNA damage-induced apoptosis." (PMID 38732110, 2024). "Because CDH13 promoter methylation is common in many human tumors, it has been suggested as an early detection and prognostic marker for human malignancies, particularly colorectal, breast, and non-small cell lung cancer (NSCLC)." (PMID 33407434, 2021). "For example, the hypermethylation of four genes, CDKN2A, cadherin 13 (CDH13), RASSF1, and APC, can be used to predict tumor progression of stage 1 non-small cell lung cancer (NSCLC)." (PMID 27895806, 2016). "Early candidate gene studies using a nested case-control analysis of patients with stage I non-small cell lung cancer (NSCLC), showed that the methylation status of four genes (p16, CDH13, RASSF1A, and APC) correlated with recurrence." (PMID 23755372, 2013).
Hypertension (13 papers, 2014 to 2025). The presence of chronic increased pressure in the systemic arterial system. "Genome-wide association studies have identified genetic variants in CDH13 that are associated with coronary artery disease, blood pressure traits, and hypertension." (PMID 37660920, 2023). "We found variant rs3096277 (CDH13—Cadherin 13) associated with hypertension (SBP≥150 mmHg and/or DBP≥90 mmHg) in individuals aged 60 years and above and SBP in younger women as well." (PMID 34793544, 2021). "The CDH13 rs4783244 polymorphism confers stronger cardio-protection, and the CDH13 rs11646213 polymorphism is associated with risk of developing hypertension." (PMID 31464655, 2019). "Moreover, one common single nucleotide polymorphism (SNP) located upstream of the Cdh13 gene has been associated with hypertension in two independent GWAS studies conducted on populations from Germany and Estonia." (PMID 37762507, 2023). "GWAS study has previously demonstrated a SNP in the Cdh13 gene to be associated with hypertension." (PMID 37762507, 2023). "Since comprehensive literature data on the role of T-cadherin in hypertension is missing, we generated Cdh13∆Exon3 mice and examined their physical stamina and blood pressure." (PMID 37762507, 2023). "In both WT and Cdh13−/− mice we observed significant alterations in systolic pressure, indicating vascular wall remodeling, a crucial aspect of endothelial dysfunction that impedes blood flow and promotes hypertension." (PMID 40109358, 2025). "Furthermore, our experimental setup revealed two potential candidate proteins (Fbln5 and Cdh13), whose expressions were critically changed in cerebral arteries compared to systemic arteries at the early-onset of hypertension in the SHR." (PMID 37660920, 2023). "Another suggested candidate gene for hypertension is represented by the Cadherin-13 gene (CDH13)." (PMID 29495593, 2018). "Two of the genes, CDH13 and GABRB1, have been associated with hypertension in a previous GWAS." (PMID 28642868, 2017).